KRAS (KRas proto-oncogene, GTPase)
Diseases named in the same sentence as KRAS in open-access papers (continued):
Sharing a sentence is not in itself a finding about the gene and the disease.
endometriosis (continued). "In fact, KRAS mutations were commonly observed in the adenomyosis (55.6%) and endometriosis (50%) among micro-dissected eutopic endometrial samples, but less frequently in the disease-free group (29.1%)." (PMID 35887822, 2022). "Epithelial cells of the endometrium, adjacent adenomyosis and co-occurring endometriosis also share KRAS mutations." (PMID 35887822, 2022). "Especially significant are KRAS mutations which are observed in adenomyosis co-occurring endometriosis with downregulated PGR expression." (PMID 35203298, 2022). "This was an unexpected result, since KRAS mutations were associated with endometriosis sustainability." (PMID 35359373, 2022). "A separate study indicated that KRAS mutations are more frequent in cases of adenomyosis with co-occurring endometriosis, low PR expression or progestin pretreatment." (PMID 35887822, 2022). "Silencing LOX and PTX3 expression using small molecules is a potential treatment strategy for reducing cell migration, invasion, and proliferation, especially in deep infiltrating endometriosis with KRAS and PIK3CA mutations." (PMID 34202354, 2021). "The prevalence of EGFR and KRAS mutations detected in the present study is only 9.7%, lower than the one detected in our previous study (21.3%) and in those studies on endometriosis (26%) and arteriovenous malformations of the brain (48%)." (PMID 34257550, 2021). "Mutations in these genes: ARID1A, PIK3CA, KRAS, are also found in ovarian cancer that is associated with endometriosis." (PMID 33805315, 2021). "Further research, both in vitro and on an animal model, is essential to identify and explain the role of KRAS mutations in endometriosis." (PMID 33805315, 2021). "Known somatic cancer-driver mutations in ARID1A, PIK3CA, and KRAS have been identified in deep endometriosis, indicating that endometriosis is a neoplastic disease." (PMID 34067626, 2021). "Although nearly half of endometriosis samples harbor KRAS mutations, the frequency is less than 10% for normal endometrium and CCC." (PMID 33809880, 2021). "As a GTPase transmembrane protein, GTP-activated KRAS has been implicated in the development of endometriosis." (PMID 32033052, 2020). "KRAS mutations are more frequent in cases of adenomyosis with co-occurring endometriosis, low progesterone receptor (PR) expression, or progestin (dienogest; DNG) pretreatment." (PMID 31857578, 2019). "Consistent with published data, samples of co-occurring endometriosis in some of our adenomyosis patients bore both KRAS and PIK3CA mutations, whereas most co-occurring leiomyoma samples harbored MED12 mutations." (PMID 31857578, 2019). "Here we apply next-generation sequencing to adenomyosis (70 individuals and 192 multi-regional samples), as well as co-occurring leiomyoma and endometriosis, and find recurring KRAS mutations in 26/70 (37.1%) of adenomyosis cases." (PMID 31857578, 2019). "In a model of genetically engineered mice harboring an oncogenic allele of KRAS resulting in benign lesions reminiscent of endometriosis, a deletion of PTEN caused progression towards the OEC, but not the OCCC." (PMID 29599905, 2018). "In terms of unique molecular features, 29% of low-grade ovarian endometrioid adenocarcinomas with concurrent endometriosis contained mutations in KRAS compared to 3% of low-grade endometrioid adenocarcinomas lacking endometriosis." (PMID 30087267, 2018). "To better understand the finding of increased KRAS in the endometrium of women with endometriosis, we investigated the association between KRAS activation and SIRT1 expression." (PMID 28754906, 2017). "For instance, somatic mutations in the KRAS gene have previously been reported in endometriosis." (PMID 40863222, 2025). "This set of observations raises the question of whether the individuals who develop endometriosis are more likely to have endometrial tissue fragments with KRAS mutations in their retrograde menstrual tissue material." (PMID 40590223, 2025).
endometriosis (continued). "KRAS is a gene known for cancer-driver mutations reported in endometriosis." (PMID 41464345, 2025). "KRAS somatic mutations were found to be more frequent in patients with deep infiltrating endometriosis or endometrioma lesions and patients with mixed subtypes, compared to those with superficial endometriosis only." (PMID 38933332, 2024). "KRAS mutations play an important role in endometriosis invasion and pathogenesis." (PMID 38999962, 2024). "They suggest that KRAS mutation and PIK3CA mutation may not be associated with progesterone resistance in terms of aggressiveness of endometriosis; however, progesterone resistance caused by KRAS mutations may affect pain." (PMID 38666954, 2024). "The objective was to determine whether somatic KRAS mutations were associated with greater disease burden in endometriosis (i.e. more severe subtypes and higher stage)." (PMID 36977195, 2023). "KRAS mutation presence was higher in subjects with deep infiltrating endometriosis or endometrioma lesions only (57.9%; 11/19) and subjects with mixed subtypes (60.6%; 40/66), compared with those with superficial endometriosis only (35.1%; 13/37) (p = 0.04)." (PMID 36977195, 2023). "Correcting endometrial “defects” can gain further momentum by the presence of cancer-driver mutations such as KRAS mutations in the endometrium of women with endometriosis and the recent introduction of therapeutics aiming to rectify the effect of these mutations for cancer treatment." (PMID 36830705, 2023). "While reports of KRAS mutations outside of codon 12 alteration in endometriosis (and malignancies) are moderately rare we cannot exclude the possibility that these may be present and not accounted for in our population." (PMID 36977195, 2023). "Interestingly, ovarian tumor cells associated with endometriosis present similar mutations in KRAS, ARID1A, and PIK3CA (a subunit of a kinase involved in tumorigenesis)." (PMID 36979957, 2023). "We hypothesized that KRAS mutations would be associated with greater anatomic disease burden in endometriosis (i.e. more severe anatomic subtypes and higher stage)." (PMID 36977195, 2023). "For instance, drugs targeting PIK3CA or MEK signals, such as alpelisib or trametinib, respectively, may theoretically offer a new treatment for women with endometriosis whose lesions have mutations in PIK3CA or KRAS." (PMID 36979957, 2023). "Since surgery involves excision of visible endometriosis disease, it is conceivable that microscopic residual endometriosis cells harboring KRAS mutations may be more likely to cause recurrent disease." (PMID 36977195, 2023). "Epithelial cells of eutopic endometrium in adenomyosis and co-occurring endometriosis share identical KRAS mutations, which points to both conditions featuring oligoclonal tissues arising from endometrial cell populations carrying a specific driver mutation that most commonly affects the KRAS gene." (PMID 38254632, 2023). "Furthermore, KRAS mutations in different tissue areas have been reported, suggesting the presence of clonal heterogeneity and that a gradual process of changes in endometriosis is possible." (PMID 34202354, 2021). "Additionally, PIK3CA or KRAS mutated clones arising in the histologically normal uterine endometrium have been proposed as the cellular origins of endometriosis." (PMID 34202354, 2021). "Mutation in the KRAS gene was detected in 29% of patients with associated endometriosis." (PMID 33803806, 2021). "Thus, our results contribute to consider KRAS variants, in particular those located in the 12th amino acid, as linked to endometriosis." (PMID 33805315, 2021).
endometriosis (continued). "Our analyses reveal the presence of oligoclonality and recurrent KRAS mutations in adenomyosis tissues, and suggest that adenomyosis and endometriosis share molecular etiology, which may explain their frequent co-occurrence." (PMID 31857578, 2019). "Mutations in the KRAS gene were found in patients with endometriosis." (PMID 31552087, 2019). "Furthermore, endometrium samples from individuals who have undergone endometrial biopsy for a reason unrelated to endometriosis have frequently shown KRAS and PIK3CA mutations." (PMID 31857578, 2019). "Additionally, one patient was found to have the same KRAS mutation in three spatially distinct endometriosis lesions." (PMID 29456620, 2018). "This association with surgical difficulty is likely influenced by the association between KRAS mutation and advanced stage disease, as the latter often requires ureterolysis to separate the ureter from surrounding adhesions and fibrosis, prior to excision of endometriosis lesions." (PMID 36977195, 2023). "However, the study also showed evidence of clonal heterogeneity in that adenomyosis, and endometriosis may contain different KRAS mutations and there can be mutations in disease free individuals." (PMID 38254632, 2023). "Indeed, one specific CAM, i.e., the KRAS (G12C) mutation, which occurs in endometrium of some women with endometriosis, has been shown to be linked with the reduced expression of progesterone receptors (PGR) in endometrial epithelial cells, conferring resistance to progestin treatment." (PMID 36830705, 2023). "Of course, although it was reported nearly two decades ago that the KRAS mutation causes endometriosis in mice and the KRAS mutation is indeed found in endometriotic lesions, there are plenty of data also showing that women with endometrium harboring KRAS mutations are apparently normal, i." (PMID 36830705, 2023). "In contrast, the discovery of identical mutations in the KRAS gene in coexisting adenomyotic and endometriotic lesions in several patients, supports the theory of a common pathogenesis of adenomyosis uteri and endometriosis and a common molecular mechanism in these diseases." (PMID 37005590, 2023). "Furthermore, somatic mutations such as in KRAS may inform a novel molecular classification of endometriosis." (PMID 36977195, 2023). "While let-7 down-regulation has been associated with elevated KRAS levels, an inverse relationship between let-7b expression and the estrogen-regulated gene cyclin D1 has also been documented as a possible mechanism for regulating cell proliferation in endometriosis." (PMID 34449536, 2021). "In addition, KRAS mutations have been found in 29% of endometriosis-associated adenocarcinoma." (PMID 34444500, 2021). "In addition, other authors have reported that the presence of hereditary polymorphisms in the let-7 microRNA-binding site of the KRAS gene leads to abnormal KRAS expression of endometrial stromal cells, as well as increased proliferation and invasion, in women with severe endometriosis." (PMID 34449536, 2021). "We have shown that: (i) KRAS-mutated adenomyotic clones originate from NE; (ii) KRAS mutations are shared by co-occurring adenomyosis and endometriosis lesions; and (iii) the presence of KRAS mutations in adenomyosis is associated with the co-occurrence of endometriosis." (PMID 31857578, 2019). "In a more recent study, KRAS mutations were identified in 29% of endometriosis-associated endometrioid cancers but in only 3% of tumors in which endometriosis was not identified, supporting the hypothesis that KRAS mutations have an important role only in EAOCs." (PMID 26413541, 2015). "Among the 40 mapped genes in genome-wide association studies, the most common mutations were identified in the protooncogenes KRAS and PIK3CA, as well as in deeply infiltrating endometriosis in KRAS and the suppressor PTEN." (PMID 40647174, 2025).
endometriosis (continued). "Evidence indicates that 79% (19/24) of patients with endometriosis have mutations in ARID1A, KRAS, and PIK3CA in the epithelial tissue of endometriotic lesions." (PMID 40860812, 2025). "In endometriosis, Let-7 microRNA is hypermethylated, which leads to decreased expression of this microRNA and inhibits KRAS expression, promoting the growth and invasiveness of ectopic endometriosis foci." (PMID 41303437, 2025). "KRAS activation in cells with positive progesterone receptors stimulates the expression of the BCL6 protein, which is implicated in the pathogenesis of endometriosis." (PMID 39903727, 2025). "For example, one recent study found that 79% (19 out of 24) of women with endometriosis exhibited mutations in genes such as ARID1A, KRAS, and PIK3CA within the epithelial cells of the endometriotic lesions analyzed." (PMID 40227624, 2025). "Another possibility is that the common cancer-related gene mutations found in endometriosis and endometrial epithelium are PIK3CA and KRAS, which are presumed to reflect a multistep carcinogenesis model in many cases." (PMID 38067342, 2023). "Curiously, subjects with KRAS mutant endometriosis appeared to be less likely to have a prior surgery before the index surgery." (PMID 36977195, 2023). "It is possible that this epidemiological observation is accounted for by a higher rate of somatic events in KRAS in non‐Caucasian individuals with endometriosis, at least in our population." (PMID 36977195, 2023). "Endometrioid adenocarcinoma arising from endometriosis shows loss of function of PTEN (21%), KRAS (20%), β-catenin (25%), and PIK3CA (46%)." (PMID 37891997, 2023). "Next-generation sequencing (NGS) has shown that endometriosis and adenomyosis involve genetic alterations such as KRAS, PIK3CA, PPP2R1A and ARID1A." (PMID 37296736, 2023). "In the endometrium, endometriosis, adenomyosis and leiomyoma, the most frequently and activating-type genetic alterations were detected in PIC3CA, KRAS, PPP2RIA and MED12, whereas ARIDIA mutations lead to a loss of function." (PMID 35887822, 2022). "The role of SIRT1 in endometriosis was previously demonstrated in mice and humans, which suggests that an increase in SIRT1 expression is associated with oncogene KRAS activation and contributes to progesterone resistance in endometriosis." (PMID 35853978, 2022). "Low levels of the let-7 expression resulted in KRAS activation and progesterone resistance in severe endometriosis." (PMID 36612107, 2022). "Let-7 microRNA is hypermethylated in endometriosis leading to decreased Let-7 expression and disinhibition of KRAS and other genes that drive endometriosis growth and invasion." (PMID 36387918, 2022). "KRAS mutations, which function to activate the MAPK pathway, play an important role in the development of endometriosis-associated cancer, including EOVC." (PMID 34150634, 2021). "Endometriosis-harboring cancer-associated somatic mutations of PIK3CA and KRAS provides new opportunities for studying the multistep processes responsible for the functional and molecular changes in this disease." (PMID 34202354, 2021). "Recently, it has been reported that cancer-associated gene mutations, such as those in KRAS and PIK3CA, are present in cases of endometriosis and adenomyosis, which are benign endometrium-related diseases." (PMID 34442357, 2021). "Given the lower frequency of KRAS mutation in EAOC compared to endometriosis, it is possible that KRAS mutation plays a different role than malignant transformation of endometriosis." (PMID 33809880, 2021). "A large number of studies have also found that patients with endometriosis have many gene mutations, including mutations in ARID1A, PIK3CA, KRAS, FBXW7, MLH1, ERBB2, CTNNB1, and PPP2R1A." (PMID 34150634, 2021).
endometriosis (continued). "Microarray analysis was also helpful to identify the pathways regulated in endometriosis in the HMOsisEC10 KRAS and HMOsisEC10 PIK3CA mutant cells." (PMID 34202354, 2021). "Among the targeted genes, KRAS and PIK3CA are most frequently mutated in the normal epithelial cells of the uterine endometrium and in endometriosis, with a higher mutant allele frequency (MAF)." (PMID 34202354, 2021). "In vitro assays showed that migration, invasion, and proliferation were significantly increased in KRAS and PIK3CA mutant cell lines, indicating that these mutations played causative roles in the aggressive behavior of endometriosis." (PMID 34202354, 2021). "Whole-exome sequencing has explored that 79% of patients with deep-infiltrating endometriosis had some harboring oncogenic driver mutations, such as ARID1A, KRAS, PIK3CA, and PPP2R1A." (PMID 34444500, 2021). "Upregulation of KRAS and phosphatase and tensin homolog (PTEN)-regulated pathways have been linked to an upregulation of the complement pathway, as seen in endometriosis." (PMID 32033052, 2020). "The KRAS gene was considered a strong candidate gene; in fact, KRAS activation determined the development of peritoneal endometriosis in 47% of mice and endometriosis-like ovarian lesions in 100%." (PMID 32143537, 2020). "Potential oncogenic mutations found included PIK3CA, KRAS, PIK3R1, and FGFR2 in benign epithelial endometrium from women with uterine fibroids, and ARID1A mutations in endometrial stroma from women with endometriosis." (PMID 31717878, 2019). "Recent reports have revealed frequent KRAS and PIK3CA mutations in NE, i.e., in uterine endometrium that are histologically normal and unaffected by endometriosis or adenomyosis." (PMID 31857578, 2019). "Accordingly, the exact contribution of KRAS and PIK3CA mutations to endometriosis remains unresolved." (PMID 31857578, 2019). "Mutations in KRAS and ARID1A have been discovered in endometriosis, including ovarian endometriosis and deep infiltrating endometriosis." (PMID 30087267, 2018). "Together with SIRT1 and BCL6, KRAS was overexpressed in the eutopic endometrium of women with endometriosis." (PMID 29750165, 2018). "The top 6 genes associated with endometriosis found in our study are CDKNB2, MAPK1, WNT4, ILA, AKT1, and KRAS." (PMID 29750165, 2018). "Decreased gene expression was noted in several genes known to promote endometriosis growth including ER‐α, ER‐ß, Cyp19a, KRAS 4A, KRAS 4B and IL‐6." (PMID 30063121, 2018). "In conclusion, microRNA Let‐7b treatment of endometriosis resulted in decreased oestrogen signalling (ER and Cyp19A1), decreased KRAS and decreased inflammatory signalling (IL‐6)." (PMID 30063121, 2018). "Particularly, activation of oncogenic KRAS and PI3K pathways and inactivation of tumor suppressor genes PTEN and ARID1A are suggested as major pathogenic mechanisms for endometriosis associated clear-cell and endometrioid ovarian cancer." (PMID 26413541, 2015). "Given the similarities between endometriosis and adenomyosis and the increased expression of KRAS in both conditions, it is hypothesized that the BCL-6 protein may also be increased in adenomyosis." (PMID 39903727, 2025). "A mouse model demonstrated that the subclonal activating mutations of KRAS can sustain endometriosis but are not sufficient for malignant transformation." (PMID 38646168, 2024). "Shared KRAS and non-KRAS mutations were found in some cases with co-occurring adenomyosis and endometriosis." (PMID 38254632, 2023).